CD4 (CD4 molecule)
Diseases named in the same sentence as CD4 in open-access papers (continued):
Sharing a sentence is not in itself a finding about the gene and the disease.
breast cancer (continued). "Similarly, in a model with concurrent subcutaneous and intracranial EMT6 breast carcinoma tumors, rejection of s.c. tumors through peri-tumoral administration of CpG ODN potentiated the infiltration of CD4+, CD8+ T cells and NK cells into established intracranial tumors." (PMID 31824260, 2019). "T cell immunity includes many different types of cells, CD4+ T cell, CD8+ T cell, memory cell, and so on, and each of them has special function on antitumor response or tumor immune escape which is revealed in lung cancer, colorectal cancer, breast cancer, ovarian cancer, and so on." (PMID 29682534, 2018). "Thus CCL18 expressed by TAMs selectively recruits circulating naive CD4+ T cells, but not memory or Treg CD4+ T cells, into breast cancer." (PMID 28290464, 2017). "Moreover, CXCR2+ MDSCs could induce breast cancer cells EMT via IL-6, and promote activated CD4+ or CD8+ T cells exhaustion partially via IFN-γ." (PMID 29383101, 2017). "The results showed that PD-1+ and γδ T lymphocytes were associated with poor OS respectively (HR = 1.60; 95%CI, 1.15–2.23 and HR = 3.34; 95%CI, 1.21–9.23), while CD3+ lymphocytes indicated better OS (HR = 0.31; 95%CI, 0.14–0.70).CD4+ lymphocytes were not prognostic markers in breast cancer." (PMID 27073890, 2016). "However, we found that CD4+ and CD8+ TILs had distinctly different patterns during tumor progression, indicating different roles of these two cell populations in the pathogenesis of breast cancer." (PMID 25968569, 2015). "Notably, our current studies also indicate that intra-tumoral CD4+ and CD8+ T cells, as well as the ratio of CD4/CD8 in TILs are all valuable and significant prognostic biomarkers for predicting the outcomes of human breast cancer." (PMID 25968569, 2015). "Furthermore, CD4+ and CD8+ T cells have opposing prognostic effects for breast cancer patients." (PMID 25968569, 2015). "However, the dynamics and roles of CD4+ and CD8+ T cells in the pathogenesis of breast cancer remain unclear." (PMID 25968569, 2015). "The frequent expression of NY-ESO-1 in our cohort could play a potential role in the application of additional immunological therapies in breast cancer, since it has been demonstrated that NY-ESO-1 can elicit strong CD8 and CD4 T-cell response in seropositive patients." (PMID 23731661, 2013). "In a murine model of breast cancer, siRNA-mediated silencing of IDO in vaccinating DC enhanced the ability of these cells to stimulate T cell proliferation and CTL effector function, decreased the induction of CD4+ CD25+ FOXP3+ Tregs, and led to enhanced control of tumor outgrowth." (PMID 23874338, 2013). "We analysed 147 women with breast cancer treated with adjuvant RT, and who were included in the KFS 00539-9-1997/SKL 00778-2-1999 prospective study aimed at evaluating the predictive value of CD4 and CD8 T-lymphocyte apoptosis for the development of radiation-induced late effects." (PMID 15328527, 2004). "In summary, CD4 + Th1 cells that expressed and secreted high levels of miR-19a-3p developed a TCM phenotype after 24 days of cell culture, and may contribute to the elevated levels of miR-19a-3p observed in the serum of patients with metastatic HER2 + breast cancer and a favorable prognosis." (PMID 41582199, 2026). "Next, to define whether the dysfunction of CD4+ and CD8+ T cells by RNase1 requires its ribonucleolytic activity, we expressed RNase1 (R1) and a catalytically inactive RNase1 mutant (R1‐H12A)[6b] in the low‐endogenous RNase1 expressing MDA‐MB‐231 breast cancer cells." (PMID 39932384, 2025). "In breast cancer mouse model, blocking KAT6A using WM-1119 inhibitor could significantly decrease MDSCs recruitment and CD4+/CD8+ T cells depletion; when WM-1119 and anti-PD-L1 antibody treatment were combined, the efficacy of MDSCs inhibition recruitment and CD4+/CD8+ T cells activation was better." (PMID 36439186, 2022).
breast cancer (continued). "Therefore, the CD103+CD11b+ DCs in the mLNs of 4T1-inoculated mice stimulated by BG might induce IFN-γ-expressing CD4+ or CD8+ effector T cells, leading to equivalent IFN-γ expression compared to control mice even in the late stage of breast cancer development." (PMID 36232335, 2022). "Moreover, through TIMER2.0 analysis, it was found that MMP9 had a significant positive correlation with CD4+ T cells, dendritic cells, macrophages, and neutrophils, indicating that MMP9 may be involved in the immune cell infiltration process of breast cancer tissues." (PMID 35069702, 2021). "In both the METABRIC and TCGA datasets, downregulation of genes such as CD4 and CD40 may indicate decreased CD4+ T cell response or decreased CD40-mediated apoptosis, both of which are correlated with tumor regression, better response to therapy, and higher overall breast cancer survival." (PMID 29796176, 2018). "Furthermore, in a murine breast cancer model, a cancer vaccine therapy employing the systemic delivery of a tumor-targeting Salmonella-based STAT3 shRNA increased the proliferation and granzyme B levels of intratumoral CD4+ and CD8+ T cells, which favored the destruction of malignant cells." (PMID 29115974, 2017). "Similar effects have been observed in studies on oral and breast cancers; CSF-1R inhibitor monotherapy resulted in depletion of M2 macrophages and an increase in CD8- and CD4-positive T cells, despite not suppressing tumor growth." (PMID 39000110, 2024). "We show that, before initiation of treatment of “cold” tumors, intratumoral heterogeneity of the distribution of CD4 + or CD8 + T cells at baseline, not the total number of T cells, is predictive of immunotherapy outcomes in these mouse breast cancer models." (PMID 38918836, 2024). "Because UMCD6 directly activates NK cells without the need for CD4 + T cells in vitro, we tested the efficacy of UMCD6 to enhance killing of xenografted breast cancer cells by using human NK cells in vivo." (PMID 38280067, 2024). "By manual annotation, the number of sequences associated with the cancer motifs increased to 10 and 13 in the TILs-CD4+ and TILs-CD8+ samples, respectively, none of them previously reported in breast cancer." (PMID 37600765, 2023). "When controlling for this variable, the higher count of CD8+ NA T cells and the greater proportion of HLA-DR+ CD4+ CM, total CD8+ T cells and CD8+ EMRA cells among breast cancer survivors compared to healthy women was no longer statistically significant." (PMID 37324393, 2023). "Unlike the CD4+ T cell transfer group, Tslp-PyMttg Rag1KO mice that received CD8+ T cells did not gain any protection against breast cancer." (PMID 35657353, 2022). "Material and Methods: Tr1 were generated in co-cultures of CD4+CD25neg T cells, autologous immature dendritic cells (iDC), and irradiated ADO-producing CD73+ or non-producing CD73neg breast cancer (BrCa) cell lines (TU)." (PMID 34442398, 2021). "On the contrary, the ER-positive breast cancer cells (MCF-7 cell line) greatly upregulated the PD-1 expression in CD4+CD25− T cells, having no significant impact on CD4+CD25+ lymphocytes." (PMID 34440813, 2021). "Meanwhile, more than 90% of naive CD4+ T cells sorted from the mammary tumors exhibited CXCR2 (CXCL1 receptor) expression, which was relatively higher than that in non-naive CD4+ T cells." (PMID 34461944, 2021). "In MMTV-PyMT spontaneous mammary carcinoma model, a unique TH1 CD4+ subset was identified in non-tumor peripheral tissues that rendered protective benefit when transferred into treatment-naïve tumor hosts challenged with 4T1 tumors." (PMID 34012451, 2021). "METTL14, ZC3H13, and APC expression levels had significant positive correlation with infiltrating levels of CD4+ T cells, CD8+ T cells, neutrophils, macrophages, and dendritic cells, and negative correlation with Treg cells in breast cancer." (PMID 33363011, 2020).
breast cancer (continued). "Next, we investigated IC, FoxP3 and Helios expression in activated CD4+CD25+ T cells, in the presence or absence of breast cancer cells." (PMID 31614877, 2019). "Breast cancer cells also upregulated the expression of PD-1, TIM-3 and/or LAG-3, but not CTLA-4, in CD4+CD25+ T cells (comprising of activated T cells and Tregs)." (PMID 31614877, 2019). "Our previous study found that breast cancers of patients in Kenya had increased immune cell infiltration, as indicated by increased recruitment of CD163+ (M2 macrophage), CD25+ lymphocytes, and CD4+ (T helper) cells compared to non-cancer tissue." (PMID 28794686, 2017). "This is compatible with a previous smaller study showing sustained depletion of CD4+, but not CD8+, T cells after FEC chemotherapy for breast cancer, although unfortunately B cell were not studied in this case." (PMID 26810608, 2016). "This study aimed to investigate the prognostic effects of peripheral blood but not tissue infiltrating CD4+CD25+ T cells for BC patients receiving DC-CIK infusions, to testify the feasibility and values of T cell subsets proportion as substitute biomarkers for breast cancer patients." (PMID 26462021, 2015). "Recent studies in a neu-expressing breast cancer model also demonstrate that the differentiation and recall function of neu-specific CD8 memory T cells are not impaired in the absence of CD4 T cells." (PMID 22046294, 2011). "TILs (i.e., CD3, CD5, CD4, PD-1) are not predictive markers in breast cancer, according to the few studies that have assessed the prognostic effects of TIL subsets in patients with breast cancer." (PMID 39507608, 2024). "In addition, Th2 cell immunity plays a critical role in regulating tumor development, and depletion of Transforming Growth Factor (TGF)-β receptors on CD4+ T cells, but not CD8+ T cells, which can halt tumor progression in breast cancer." (PMID 36467403, 2022). "CD4+ T cells collected after 12 days of culture (T12) were restimulated polyclonally without exogenous IL-2 for the next 3 days in the presence or without (T15M and T15, respectively) MDA-MB-231 breast cancer cell line expressing PD-L1." (PMID 34439305, 2021). "The distribution of CD4+ and CD8+ T cells within blood vessels and mammary tumors of the IT group revealed that non-contact electric fields of ECCT may direct the spreading of these lymphocytes from blood vessels to tumor areas, including necrotic areas in it." (PMID 34164110, 2021). "Previous studies confirmed that in breast cancer, tumor-induced Bregs promote tumor metastasis by converting dormant CD4+CD25− T cells into CD4+CD25+Foxp3+ Tregs, while in the absence of tumor-induced Bregs, the conversion of Tregs was significantly reduced and tumor metastasis was blocked." (PMID 32456622, 2020). "However, breast cancer has a more aggressive clinical course and poorer outcome in HIV+ patients than in general population, without correlation with the CD4 or virus particles count." (PMID 29021819, 2017). "However, in contrast to breast cancer cells, Slit2N did not have any effect on the downregulation of either CXCR4/CCR5 or CD4 expression, ruling out down-modulation of HIV-1 receptors/co-receptors as a mechanism of action for Slit2." (PMID 23294842, 2013). "When tested for the ability to stimulate allogeneic CD4+ T cells and CD8+ T cells (data not shown), mature MDDC prepared from cryopreserved PBMC of cancer patients (five breast cancer and two colon cancer patients) were not significantly different from those of healthy donors." (PMID 17477875, 2007). "Furthermore, the splenic CD4+ and CD8+ T cells from the three groups all could not inhibit mouse 4T1 breast cancer cells and even promoted the proliferation of 4T1 cells." (PMID 30833570, 2019).
breast cancer (continued). "Due to the small sample size, the relationships observed between CD4 and CD8 levels and poorer City of Hope questionnaire total Quality of Life score, and neuropsychological performance may not extend to all manner of active treatment breast cancer patients experiencing other modes of treatment." (PMID 32434503, 2020).
co-infection (867 papers, 2006 to 2026). "CMV co‐infection was associated with a robust, 36‐fold expansion of GzmB+Perforin+ CD4+ T cells among EBV/HSV‐seropositive individuals, with comparable frequencies observed in both RA patients and controls." (PMID 41235706, 2025). "Cochran-Armitage trend test, cluster analysis, and Kruskal-Wallis test were used to analyze the associations between CD4+ T cells strata and pathogen detection rates/co-infection complexity." (PMID 41488483, 2025). "HIV/HCV co‐infection has also been associated with a lower level of immune restoration among people who start highly active antiretroviral therapy, with CD4+ cell counts sometimes remaining low despite HIV suppression." (PMID 39656170, 2025). "Nevertheless, a significant percentage of these patients continue with a low count of CD4+ T-cell, even after virological suppression, and remain susceptible to coinfections." (PMID 38932341, 2024). "Ascaris single and coinfection were associated with a rise of CD4-CD8α+FoxP3+ Treg in the lymph nodes draining the small intestine and liver." (PMID 39140728, 2024). "Significant associations with co-infection were found for females, viral load exceeding 1000 copies/ml, single marital status, educational level unable to read and write or read and write, CD4 count between 351 and 500 cells/ml and surgical history." (PMID 38693473, 2024). "SIV co-infection of latent Mtb infection caused asignificant increase in percentage of CD4+TCM in BAL at week 11(peak viremia prior to cART + 3HP treatment) (P < 0.0001)." (PMID 39257997, 2024). "The bivariate analysis result showed that educational levels, ART status, HAART durations, WHO stage and CD4 cell counts were significantly associated with TB/HIV co-infection." (PMID 40809574, 2024). "Overall, this data shows that H. pylori co-infection was associated with higher CD4+ T cell count and reduced HIV-1 viral load in HIV-positive individuals, regardless of ART status." (PMID 38494500, 2024). "These patients remain chronically symptomatic with hypersplenism, for example with anemia, leukopenia, and thrombocytopenia, and are at risk of severe co-infection due to low CD4+ count." (PMID 38491526, 2024). "This aligns with established evidence that a weakened immune system, as indicated by low CD4 counts, is a major risk factor for TB co-infection among HIV-positive individuals." (PMID 38995935, 2024). "Previous studies associated CD4+ levels of <350 cells/μL with hepatic events in patients with HIV/HCV co-infection and of <200 cells/mm3 with liver fibrosis in HIV patients." (PMID 38787212, 2024). "Our study demonstrates that H. pylori co-infection was associated with higher CD4+ T cell count and lower HIV-1 viral load in HIV-positive patients, regardless of ART status." (PMID 38494500, 2024). "In conclusion, our results based on a large cohort show that being male, older age, HBV/HCV co-infection, lower baseline CD4 + T cell count and lower CD4/CD8 ratio increase the risk of immunological non-response." (PMID 38287246, 2024). "In PWH and CMV coinfection, IL-27 plasma levels were negatively correlated with viral load and positively associated with CD4 T cell counts suggesting a beneficial effect in CD4 T cell reconstitution in CMV infected PWH." (PMID 38966644, 2024). "Coinfection was associated with a lower frequency of dual-function HIV specific CD4 T cells and lower CD4 IFN-γ and TNF-α production in responding cells." (PMID 37644394, 2023). "The risk factors for HIV/TB co-infection included a low CD4+ T cell count, smoking, intravenous drug use and several other sociodemographic and clinical factors." (PMID 37674103, 2023). "Most studies in South Africa reported an association between HBV co-infection and CD4 less than 200 cells/mm3." (PMID 37545964, 2023).
co-infection (continued). "Nineteen studies reported the risk factors of HIV/TB co-infection, which primarily included CD4+ T cell count ≤ 200/μL, smoking, intravenous drug use, unemployment, male sex, and senior citizen status." (PMID 37674103, 2023). "Our multivariate analysis confirmed that higher‐severity HIV status, including WHO Stage IV, HBV/HCV coinfection and CD4 counts <200 cells/μl, was associated with a higher risk for comorbidities." (PMID 38054578, 2023). "Active TB co-infection changed the functional abilities of SARS-CoV-2–specific CD4+ T cells and caused a reduction of their polyfunctional abilities." (PMID 37841282, 2023). "We also found that a lower baseline CD4 count at the time of HIV diagnosis was associated with mortality in patients with TB/HIV coinfection." (PMID 36749231, 2023). "In humans, majority of C. neoformans infections were related with CD4+ T cell deficiency due to HIV co-infection, while IL-17-producing CD4+ T (Th17) cells were needed for vaccine-mediated protection against C. neoformans." (PMID 35720334, 2022). "In a multiple logistic regression model, we identified a CD4+ T lymphocyte value < 200 cells/μL to be significantly associated with the odds of C. cayetanensis co-infection among PLWH, the adjusted odds ratio was 2.11 (95% CI: 1.17, 3.79), p = 0.01." (PMID 35889126, 2022). "Taken together, we demonstrate that a low pre-ART CD4 + cell count and coinfection with HCV are associated with immune recovery in HIV patients." (PMID 35135485, 2022). "Intravenous drug use, and lower CD4+T cells count are the most important risk predictors of co-infection." (PMID 35239716, 2022). "Numerous studies have found that hepatitis B virus, hepatitis C virus, and cytomegalovirus coinfections were associated with poor CD4 + T cells immune recovery in HIV‐1‐infected individuals on ART." (PMID 35114959, 2022). "Our study showed that HIV patients with CD4+ T cells count less than 350 cells/mm3 were at 13.84 times higher risk of having triple co-infections as compared to patients with CD4+ T cells more than 350 cells/mm3." (PMID 35239716, 2022). "Bacterial co-infection and predisposing factors: Bacterial infection was significantly higher (p = 0.02) among particiapnts with CD4 count < 200 cells/μl." (PMID 35672713, 2022). "The findings of this study and the results of other studies conducted in Ethiopia and other countries indicated that, HIV patients with a lower CD4 counts at a baseline are at a higher risk of co-infection with TB10,18,45." (PMID 36182998, 2022). "We previously found that the annual rate of CD4 T-cell count change was associated with CMV co-infection and anti-CMV IgG titers." (PMID 35336860, 2022). "HBV/HIV coinfection, especially in cases with low nadir CD4+T cell counts, is associated with increased liver disease progression and liver-related mortality." (PMID 36431096, 2022). "Multivariable analysis demonstrated that low pre-ART CD4 + cell count and coinfection with HCV were associated with immune recovery of the HIV patients." (PMID 35135485, 2022). "Several cross-sectional studies propose HIV-1 DNA load in PBMCs, CD4 + T-cell counts after 10 years from seroconversion, high viral loads and co-infection with hepatitis C, as predictors of loss of LTNP status." (PMID 35346235, 2022). "Chronic HPgV-1 coinfection in HIV was associated with significantly lower numbers of Fas-expressing CD4+ T cells when compared to HIV mono-infected." (PMID 35707535, 2022). "The CD4+ count at co-infection was the only variable independently associated with reactivation whereas male sex and CD4 count at co-infection were independently associated with death in CDR patients." (PMID 34591866, 2021). "Liver fibrosis progression is more rapid in the context of HIV-HCV coinfection and is associated with lower CD4 cell counts." (PMID 35222296, 2021).